CGA (glycoprotein hormones, alpha polypeptide)
Description:
Shared alpha chain of the active heterodimeric glycoprotein hormones thyrotropin/thyroid stimulating hormone/TSH, lutropin/luteinizing hormone/LH, follitropin/follicle stimulating hormone/FSH and choriogonadotropin/CG. These hormones bind specific receptors on target cells that in turn activate downstream signaling pathways.
Synonyms: CG-alpha; HCG; GPHa; GPHA1; FSHA; LHA; TSHA; GPA1
Tractability: Small molecule: a structure with a bound ligand is known. Antibody: UniProt places it where antibodies can reach, with high confidence; its Gene Ontology location is reachable by antibodies, with high confidence; UniProt predicts a signal peptide or a membrane-spanning region.
Target class: Secreted protein
Gene: Protein-coding gene on chromosome 6 (87,085,498 to 87,095,106, reverse strand). Ensembl gene ENSG00000135346.
Subcellular location: Secreted
Pathways (Reactome):
Metabolism: Androgen biosynthesis; Mineralocorticoid biosynthesis; Thyroxine biosynthesis
Metabolism of proteins: Glycoprotein hormones; Reactions specific to the complex N-glycan synthesis pathway
Signal Transduction: G alpha (s) signalling events; Hormone ligand-binding receptors
Gene expression (Transcription): TFAP2 (AP-2) family regulates transcription of growth factors and their receptors
Gene Ontology:
Molecular function: follicle-stimulating hormone activity; hormone activity; protein binding
Biological process: G protein-coupled receptor signaling pathway; positive regulation of steroid biosynthetic process; regulation of signaling receptor activity; follicle-stimulating hormone signaling pathway; hormone-mediated signaling pathway; MAPK cascade; ovarian follicle development; positive regulation of cell migration; positive regulation of cell population proliferation; positive regulation of transcription by RNA polymerase II; spermatogenesis; insulin secretion involved in cellular response to glucose stimulus
Cellular component: extracellular region; follicle-stimulating hormone complex; pituitary gonadotropin complex; receptor complex; Golgi lumen
Genetic constraint (gnomAD): Loss-of-function variants: 2 observed, 7.91 expected, observed/expected ratio (o/e) 0.25, 90% interval 0.1 to 0.8. That is too few expected variants to judge how well the gene tolerates losing a copy. Missense variants: 74 observed, 105.6 expected, observed/expected ratio (o/e) 0.7, 90% interval 0.58 to 0.85. Synonymous variants: 50 observed, 44.23 expected, observed/expected ratio (o/e) 1.13, 90% interval 0.9 to 1.43.
Homologues: Orthologues: chimpanzee CGA (95% identical), rabbit CGA (77% identical), dog CGA (76% identical), mouse Cga (76% identical), pig CGA (75% identical), rat Cga (74% identical), macaque CGA (71% identical), tropical clawed frog cga (70% identical), guinea pig CGA (69% identical), zebrafish cga (56% identical), zebrafish CGA (52% identical).
Diseases named in the same sentence as CGA in open-access papers:
CGA is named in the same sentence as 258 diseases in open-access papers, as found by Europe PMC text mining. Sharing a sentence is not in itself a finding about the gene and the disease. The quoted sentences say what the papers report.
neuroendocrine tumors (119 papers, 1998 to 2026). "CgA has recently garnered interest not only for its diagnostic utility in neuroendocrine neoplasms, but also for its role in modulating glucose metabolism, lipid regulation, and immune responses." (PMID 41480370, 2025). "Elevated circulating levels of CgA are associated with nearly all types of neuroendocrine tumors, including PPGL." (PMID 38669419, 2024). "Elevated circulating levels of CgA have been associated with many neuroendocrine tumors as well as PPGLs." (PMID 34833055, 2021). "Chromogranin A (CgA) is the most widely accepted biomarker for neuroendocrine tumors (NET) but its diagnostic accuracy is dependent on tumor type and the use of proton-pump inhibitors (PPI)." (PMID 32887459, 2020). "Serum CgA is considered as the diagnostic biomarker for gastroenteropancreatic neuroendocrine neoplasms and has been utilized in clinical applications." (PMID 31750312, 2019). "The bioactive peptides of CgA have shown promise as prognostic and diagnostic biomarkers for neuroendocrine tumors, cardiac disease, burn trauma and stress in humans." (PMID 28049540, 2017). "In previous decades, chromogranin A (CgA) has been demonstrated to be the most promising biomarker for the diagnosis of neuroendocrine tumors (NETs), but its diagnostic value is still controversial." (PMID 25894842, 2015). "Immunohistochemical markers associated with neuroendocrine tumors, such as Syn, CgA and NSE, were positively stained." (PMID 25295074, 2014). "While CgA levels are generally associated with tumor burden and differentiation status, up to 30–50% of patients with neuroendocrine neoplasms may exhibit normal CgA values, which can impact diagnostic and monitoring accuracy." (PMID 41300999, 2025). "The serum CgA level increases with the progression of type 1 diabetes, and it is associated with the development of enterochromaffin-like cell hyperplasia and autoimmune gastritis, from which neuroendocrine tumors can arise." (PMID 32684986, 2020). "Chromogranin-A (CgA), commonly expressed in neuroendocrine tumors, may be associated with poorly differentiated PCa." (PMID 29312648, 2017). "Chromogranin A (CgA), a glycoprotein prohormone, modulates various processes including angiogenesis and innate immunity, and its higher levels are detected in neuroendocrine tumors and inflammatory disorders." (PMID 41753254, 2026). "Although serum CgA levels are widely used for diagnosing and monitoring neuroendocrine tumors, their clinical utility is limited by low specificity." (PMID 41480370, 2025). "While chromogranin A (CgA) is a widely used biomarker for neuroendocrine tumors, its role in diagnosing ANETs is limited, particularly in early-stage tumors." (PMID 40271189, 2025). "Among these, CgA stands as a primary neuroendocrine marker, demonstrating marked elevation across diverse neuroendocrine neoplasms." (PMID 41573638, 2025). "Increased CgA levels are found in neuroendocrine tumors, which is also confirmed by the results of this study." (PMID 39451760, 2024). "In thoracic neuroendocrine tumor studies, serum chromogranin A (CgA) has been predominantly discussed in the context of L-NETs, albeit with limited sensitivity and prediction accuracy." (PMID 39061142, 2024). "The neuroendocrine tumors display almost 100% positive staining for Syn, which is the most sensitive marker, and about 53% positive for CgA, which is significantly lower than the positive rates of Syn and CD56." (PMID 39465709, 2024). "Immunohistochemical markers such as chromogranin A (CgA) and synaptophysin (Syn) are crucial for confirming neuroendocrine differentiation of tumors and are indispensable in the diagnosis of neuroendocrine tumors." (PMID 39507752, 2024). "Chromogranin A (CgA) is a protein found in cells of neuroendocrine origin and has been the most widely used biomarker for neuroendocrine neoplasms in general to date." (PMID 37770647, 2024).
neuroendocrine tumors (continued). "Our analysis also tried to find a link between serum levels of common neuroendocrine tumor markers such as chromogranin A (CgA), serotonin, and 5-hydroxy indoleacetic acid (5-HIAA) and bone metastases in PanNETs." (PMID 37510802, 2023). "In patients with PCs, the increased levels of CgA suggest the presence and/or progression of neuroendocrine tumours or subpopulations." (PMID 36527470, 2023). "In a 2016 Russian study, the authors showed that the highest concentration of CgA was found in patients with neuroendocrine neoplasms of the small intestine, colon, and pancreas." (PMID 37444393, 2023). "Previously, CgA testing has been used to measure the amount of CgA in the blood but has been typically reserved for the diagnosis and management of patients with neuroendocrine tumors." (PMID 37623863, 2023). "CgA should be included as a tool for monitoring the evolution of PC: to identify the presence of neuroendocrine tumour subpopulations and to assist physicians with patient follow-up and treatment decisions." (PMID 36527470, 2023). "The European Neuroendocrine Tumor Society (ENETS) recommends the systematic determination of CgA and urinary 5-HIAA for gastrointestinal NETs, for jejuno-ileal NETs these are the two systematic examinations to be performed in the first line." (PMID 36268349, 2022). "In accordance with the updated guidelines of the Polish Network of Neuroendocrine Tumours, we advise utilizing CgA for monitoring during treatment and as a prognostic biomarker in colorectal NEN." (PMID 36233409, 2022). "Abnormal levels of CgA, detected by immunoassay, are present in the blood of patients with neuroendocrine tumors or with other diseases, such as cardiovascular, gastrointestinal, renal, and inflammatory diseases." (PMID 36559048, 2022). "Chromogranin A (CgA) is found in the secretory granules of all neuroendocrine cells and is one of the most widely used biomarkers for the diagnosis of neuroendocrine tumors." (PMID 35163032, 2022). "Both PDX tumors stained positive for the neuroendocrine tumor markers chromogranin A (CgA) and synaptophysin (SYP), but only the NEC913 PDX tumor stained positive for somatostatin receptor 2 (SSTR2)." (PMID 35454817, 2022). "In this study, the neuroendocrine markers CgA and Syn were recommended by the Chinese gastroenteropancreatic neuroendocrine tumor pathology expert group." (PMID 36035314, 2022). "CgA is found in most neuroendocrine tumors, and also in local PPGLs, but in the latter this test is inferior to metanephrines, although recommended by some." (PMID 35205664, 2022). "Serum levels of CgA and CgB are significantly higher in the presence of carcinoid heart disease among patients with neuroendocrine tumors." (PMID 34204153, 2021). "There is a correlation between serum CgA levels and endocrine tumor growths in several neuroendocrine tumors (NETs)." (PMID 33485291, 2021). "Chromogranin A (CgA) is a well-known marker measured in neuroendocrine tumors that is commonly used for their diagnosis." (PMID 34833055, 2021). "CgA is known as an important biomarker of diabetes and cardiovascular diseases in addition to neuroendocrine tumors." (PMID 34204153, 2021). "Numerous immunoassays have been developed to measure the levels of chromogranin A (CgA), a useful biomarker for diagnosing and monitoring generally heterogeneous neuroendocrine tumors (NETs)." (PMID 34943638, 2021). "Chromogranin A (CgA) is a useful biomarker for diagnosis and monitoring of the extremely heterogeneous neuroendocrine tumors (NETs)." (PMID 34943638, 2021). "In neuroendocrine tumors, plasma chromogranin A (CgA) is one of the most commonly evaluated biomarkers in patients with neuroendocrine tumors." (PMID 34298822, 2021). "Despite its varying sensitivity and decreased specificity, chromogranin A (CgA) is the most widely used biomarker for neuroendocrine tumors." (PMID 32887459, 2020).
neuroendocrine tumors (continued). "Microscopy and immunohistochemistry uncovered a neuroendocrine tumor, staining positive for chromogranin A (CgA), synaptophysin and somatostatin, with a Ki67 = 1%." (PMID 32825782, 2020). "As in the case of our patient, such neuroendocrine tumors usually present with liver metastasis since neoplastic cells from the pancreas enter the enterohepatic circulation and plasma chromogranin A (CgA) is usually elevated." (PMID 32903471, 2020). "Serum CgA and CgB have higher levels in blood and correlate with each other in neuroendocrine tumors of various locations including foregut, midgut and adrenal medulla." (PMID 32684986, 2020). "Chromogranins are associated with the carbohydrate metabolism: CgA is known to play a significant role in the development and pathogenesis of type 1 diabetes and it is associated with some type 1 diabetes complications, which could develop into neuroendocrine tumors." (PMID 32684986, 2020). "Increased CgA level upon PPI treatment decreases the clinical utility of CgA in neuroendocrine tumors." (PMID 32887459, 2020). "The common serological markers of PNETs, which develop from neural crest cells, are CgA and neuron-specific enolase, for each of which an abnormal increase often indicates the possibility of a neuroendocrine tumor." (PMID 31296241, 2019). "Circulating CgA levels are elevated in a variety of neuroendocrine tumors (NETs), including carcinoids, pancreatic NETs, pheochromocytoma, paraganglioma, and neuroblastoma." (PMID 30833285, 2019). "Recent studies evaluated CgA as a valuable biomarker in various stressful diseases including neuroendocrine tumors, cardiovascular disorders, atopic dermatitis, ulcerative colitis and diabetes mellitus." (PMID 31750312, 2019). "Chromogranin A (CgA) is a plasma biomarker widely used in the follow-up of patients with neuroendocrine neoplasms (NENs)." (PMID 29723285, 2018). "CgA and Syn are specific biomarkers for the identification of neuroendocrine tumors, and were analyzed in the current study." (PMID 30290620, 2018). "Plasma CgA-levels have been suggested to indicate the presence of neuroendocrine tumors with high sensitivity and specificity (70% to 93%)." (PMID 29232390, 2017). "Neuroendocrine tumors (NETs) comprise a heterogeneous group of malignancies that express neuropeptides as synaptophysin, chromogranin A (CgA), and specific neuronal enolase (NSE), among others." (PMID 28194370, 2017). "Taken together, our results clearly demonstrate that CgA is an appropriate histological marker to establish the diagnosis of neuroendocrine tumors in the colon and rectum." (PMID 29232390, 2017). "The flow cytometric analysis showed that major population of single cells prepared from PNET specimens prior to the analysis was positive for CgA, a marker of neuroendocrine tumor cells." (PMID 28941156, 2017). "Increased levels of CgA have been immunologically detected in the blood of patients with neuroendocrine tumors or with tumors that undergo neuroendocrine differentiation, including prostate, breast and non-small cell lung cancer." (PMID 27683038, 2016). "In retrospect, our interpretation of the peripheral contrast enhancement of the tumor together with a slightly elevated CgA as suggestive of a neuroendocrine tumor was incorrect." (PMID 27631424, 2016). "For these reasons CgA is widely used as a serological marker for neuroendocrine tumor diagnosis or for monitoring tumor progression/regression after therapy." (PMID 27683038, 2016). "Until the results of a study on a larger population of patients are published, we can only rely on the knowledge that serum levels of CgA present a reliable marker for neuroendocrine tumors." (PMID 26170833, 2015). "At present, CgA is used as a marker for neuroendocrine tumors since it represents overall activity of the endocrine system in the body." (PMID 26170833, 2015).
neuroendocrine tumors (continued). "In particular, measurement of CgA levels in plasma can be used to diagnose or monitor the progression of neuroendocrine tumors." (PMID 24523932, 2014). "CgA is currently the only granin whose measurement is routinely used by clinicians for the diagnosis of neuroendocrine tumors." (PMID 24523932, 2014). "CgA measurement in plasma has a central role in the diagnosis and treatment follow-up of neuroendocrine tumors, since these tumors often produce vast amounts of CgA." (PMID 24532383, 2014). "The presence and over-expression of prohormone convertases 1-3 in neuroendocrine neoplasms suggested that CgA was altered at a post-translational stage via this enzymes." (PMID 24260544, 2013). "Concordance between the three pathologists regarding neuroendocrine tumor involvement was 96.4% on H&E staining and 97.4% on CgA IHC." (PMID 22720672, 2012). "We have previously developed an oncolytic serotype 5 adenovirus (Ad5) with chromogranin-A (CgA) promoter-controlled E1A expression, Ad[CgA-E1A], with the intention to treat neuroendocrine tumors, including carcinoids." (PMID 20111709, 2010). "In conclusion, the double-targeted Ad[CgA-E1A-miR122] virus has potential for the treatment of neuroendocrine tumors that metastasize to the liver." (PMID 20111709, 2010). "The CgA gene is highly expressed in neuroendocrine tumors and CgA is known to be a sensitive and specific tumor maker for neuroendocrine tumors." (PMID 20111709, 2010). "We demonstrated that the CgA promoter is functional when inserted in an adenovirus genome and retains selectivity for neuroendocrine cells, including neuroblastomas and neuroendocrine tumors of the ileum, also known as midgut carcinoids." (PMID 20111709, 2010). "Both tumour markers, platelet serotonin and CgA, can be reliably used for diagnosis of neuroendocrine tumour and for monitoring the outcome of treatment in individual patients." (PMID 16800893, 2006). "Determination of platelet serotonin and plasma CgA is useful for detection of neuroendocrine tumour and to evaluate therapy efficiency." (PMID 16800893, 2006). "Granule proteins located to dense core, for example, chromogranins, are also used as general markers of neuroendocrine differentiation since almost all neuroendocrine tumours express CgA." (PMID 12771991, 2003). "In contrast, CgA was present in all neuroendocrine tumours examined (25 out of 25 pancreatic endocrine tumours, 19 out of 19 pheochromocytomas, 14 out of 14 neuroblastomas and 15 out of 15 ileal carcinoids)." (PMID 12771991, 2003). "In the other neuroendocrine tumours, CgA was abnormal in 23/28 cases (sensitivity 82%) and in 6 it was the only circulating marker of disease." (PMID 11237384, 2001). "Chromogranin A (CgA), a major protein of chromaffin granules, has been described as a potential marker for neuroendocrine tumours." (PMID 10408695, 1999). "Nowadays, many studies suggest that the increased release of CgA from neuroendocrine tumor cells is involved in the regulation of tumor growth and progression and that circulating CgA is a useful serum marker for diagnosing various types of neuroendocrine tumors." (PMID 39975592, 2025). "Apart from being a neuroendocrine tumor marker, CgA is elevated in several diseases." (PMID 40370467, 2025). "Furthermore, NSE and Syn are frequently employed in conjunction with CgA to monitor the biological behavior of neuroendocrine tumors and assess therapeutic response." (PMID 41573638, 2025). "Although primarily used as a biomarker for neuroendocrine tumors, elevated CgA levels have been observed in metabolic and inflammatory disorders such as diabetes, thyroid disease, and cardiovascular conditions, suggesting its broader role in metabolic regulation and immune signaling." (PMID 41480370, 2025). "Serum levels of CgA are lower with lung neuroendocrine tumors than other sites." (PMID 39233931, 2024). "Chromogranin A (CgA) is a well-known biomarker for neuroendocrine tumors (NETs)." (PMID 37954718, 2023).